VCAM1 (vascular cell adhesion molecule 1)
Diseases named in the same sentence as VCAM1 in open-access papers (continued):
Sharing a sentence is not in itself a finding about the gene and the disease.
autoimmune disease (19 papers, 2016 to 2024). A disorder resulting from loss of function or tissue destruction of an organ or multiple organs, arising from humoral or cellular immune responses of the individual to their own tissue constituents. "Research has also demonstrated that polymorphisms in the ICAM-1 and VCAM1 genes are associated with an increased genetic risk for various autoimmune diseases." (PMID 39409189, 2024). "Because of its wide distribution in human tissues and organs, VCAM-1 has been implicated in the development of a variety of pathophysiological states in the brain and in the body periphery, including autoimmune diseases, cardiovascular disease, and infections." (PMID 30355978, 2018). "Additionally, VCAM-1 has been shown to be associated in cancer, autoimmune diseases." (PMID 37550786, 2023). "Several other molecules are shown to be induced by VIP in allergic and autoimmune diseases, including TSLP, TGF-β, and VCAM-1, all of which are implicated in the pathogenesis of EoE." (PMID 38391908, 2024). "VCAM-1 exerts pro-inflammatory function in many autoimmune diseases and helps the migration and adhesion of macrophages and T cells to tissue." (PMID 34568330, 2021). "The potential aging-related overexpression of IL-18 could lead to the promotion of Th2-mediated diseases and autoimmune diseases through pathways involving the upregulation of vascular cell adhesion protein 1 (VCAM-1) and T cell-mediated IL-17." (PMID 37175661, 2023). "Autoimmune diseases in G6PD deficient patients may be triggered by activation of TGF-β/NADPH oxidases/ROS signaling, the expression of ICAM-1 and VCAM-1, and the adhesion of leukocytes to the endothelial cells with endothelial to mesenchymal transition." (PMID 37753082, 2023). "Blockade of EC-mediated anti-VCAM1 interactions via biologics, including natalizumab and vedolizumab, has proven effective in ameliorating T-cell homing to inflamed tissues in autoimmune disease and may show promise in blocking immune complications attendant to VCAs." (PMID 37915586, 2023). "Several data have reported that the interactions between VCAM-1 and VLA-4 (α4β1) is crucial in the progression of autoimmune diseases." (PMID 36467095, 2022). "VCAM-1 and ICAM-1 are two important cell adhesion molecules, which participate in the adhesion and migration of immune cells and play an important role in the pathological process of inflammation, tumor metastasis, and autoimmune diseases." (PMID 35674582, 2022).
depression (19 papers, 2015 to 2025). "Higher levels of ICAM-1 and VCAM-1 have also been associated with schizophrenia, depression, and bipolar disorder, and interestingly, higher ICAM-1 levels have been associated with BBB hyper-permeability." (PMID 36904292, 2023). "Several proteins, among them Insulin-like Growth Factor-1 (IGF-1), Metalloproteinase type 1 (TIMP-1), and Vascular Cell Adhesion Molecule type 1 (VCAM-1) were reported to mediate association between dementia and depression." (PMID 35326481, 2022). "At T2 follow-up, lower sleep quality was associated with higher levels of vascular cell adhesion molecule 1 and interleukin 8, but also with higher scores for anxiety, depression, and post-traumatic stress disorder." (PMID 36062000, 2022). "One paper further listed VCAM-1 as a presumed marker of endothelial activation and dysfunction and concluded that VCAM-1 could potentially be used as a biomarker for cerebrovascular causes of depression." (PMID 39963633, 2025). "For instance, studies of serum IL-6, ICAM-1, and VCAM-1 levels in AD patients and depression patients show some differences." (PMID 38247923, 2024). "Using type of depression as the outcome variable, multivariate regression analysis revealed VCAM-1 to be a significant predictor of MDD (B = 0.003, 95% CI 0.001–0.007, p = 0.004) in the acute stage of the disorder." (PMID 39056795, 2024). "Increased levels of soluble VCAM-1 have been reported in another study of severe depression, which supports the existence of endothelial damage and cardiovascular risk." (PMID 34093252, 2021). "VCAM-1 serum levels also appeared to be greater in AD patients compared to depression patients." (PMID 38247923, 2024). "The majority of previous studies reported either unchanged or elevated expression of VCAM-1 and ICAM-1, or their soluble forms, in major depression and bipolar disorder." (PMID 39056795, 2024). "Increased levels of soluble VCAM-1 and VWF have been reported in other studies in major depression, and support the existence of endothelial damage and cardiovascular risk." (PMID 27598970, 2016). "Patients with major depressive disorder typically exhibit higher levels of adhesion molecules related to proinflammatory conditions like ICAM-1, while those with bipolar disorder show an increase in anti-inflammatory molecules like VCAM-1." (PMID 39056795, 2024). "In patients suffering from depression, soluble forms of ICAM-1 and VCAM-1 were increased, as opposed to reduced levels of BDNF." (PMID 32372985, 2020).
prostate carcinoma (19 papers, 2009 to 2024). A carcinoma that arises from epithelial cells of the prostate gland. "High vascular cell adhesion molecule (VCAM-1) expression is significantly associated with clinical stage and distant metastasis in prostate cancer." (PMID 36035183, 2022). "Osteoblast-secreted CCN4 participates in prostate cancer bone metastasis through the VCAM-1/integrin α4β1 system." (PMID 38994113, 2024). "WISP-1 enhanced the expression of VCAM-1 in prostate cancer cells and promotes the expression of integrin α4β1 in osteoblasts via MAPK pathway." (PMID 37037822, 2023). "L1 methylation is inversely associated with inflammation markers such as vascular cell adhesion molecule-1 (VCAM-1) and is associated with incidence of prostate cancer, a highly age-related disease." (PMID 35968782, 2022). "Calcitriol and vitamin D3 analogs suppress the secretion of proteolytic enzymes in breast and prostate cancer cells while also inhibiting the expression of receptors of cell-adhesion molecules, e.g., vascular cell-adhesion protein 1 (VCAM-1)." (PMID 35565690, 2022). "CCN4 promotes adhesion of prostate cancer cells to bone via upregulation of VCAM1 and integrin α4β1 expression on osteoblasts and migration of prostate cancer cells themselves." (PMID 34228239, 2021). "Treatment with kaempferol causes a downregulation of proliferation in human prostate cancer through suppression of proliferating-cell nuclear antigen (PCNA) and vascular cell adhesion molecule-1 (VCAM-1)." (PMID 29736177, 2018). "WISP-1/VCAM-1/integrin α4β1 axe promoted the adhesion of prostate cancer cells to osteoblasts." (PMID 37037822, 2023). "Among these, the CD44—a multifunction cell surface adhesion receptor that is expressed by prostate cancer cells—binds to vascular cell adhesion molecule 1 (VCAM-1), and other factors, including insulin-like growth factor 1 (IGF1), insulin, and interleukin-17 (IL-17) are able to boost this process." (PMID 33535541, 2021). "Moreover, serum VCAM-1 was the only prognostic factor for patients with stage 3 and stage 4 rectal cancer patients while, in prostate cancer, serum VCAM-1 achieved the status of independent predictor after adjusting for the standard postoperative clinicopathological features." (PMID 26881177, 2016). "It has also been found that IL-17 increases the expression of VCAM-1 in vascular endothelial cells through CD44-VCAM-1 interaction, thereby enhancing the adhesion of PCa cells to vascular endothelial cells to promote prostate cancer metastasis." (PMID 39906741, 2024). "We previously showed that HEGU and licoricidin reduce the invasion, adhesion, and migration of DU145 prostate cancer cells, as well as the secretion of MMP-9, ICAM-1, and VCAM-1." (PMID 27314329, 2016). "Significantly, VCAM1 expression was elevated in vascular endothelial cells under the stimulation of IL-17 and insulin/IGF1, which strengthened the adhesion between PCa cells and vascular endothelial cells and promoted prostate cancer metastasis." (PMID 37494663, 2023).
glioblastoma (18 papers, 2014 to 2026). The most malignant astrocytic tumor (WHO grade IV). "We also identified expression of ICAM-1 and VCAM-1, the cognate receptors for the CD11a and CD49d integrins respectively, at the gene level within glioblastoma-associated clusters via scRNA-seq." (PMID 35464424, 2022). "Moreover, the presence of upregulated endothelial VCAM-1 in close association with the tumor front in human glioblastoma tissue provides confidence that VCAM-MPIO MRI remains relevant in more infiltrative disease." (PMID 35312755, 2022). "Indeed, we identified expression of ICAM-1 and VCAM-1 at the gene level within glioblastoma-associated clusters via scRNA-seq." (PMID 35464424, 2022). "As glioblastoma is characterized by high levels of microvascular proliferation, we next evaluated if endothelial/pericytic VCAM-1 (VLA-4’s ligand) was also increased in tumor." (PMID 40244705, 2025). "The concentration of 100 μM of G721-0282 was found to completely inhibit VCAM-1 mRNA expression in glioblastoma cells." (PMID 39607670, 2025). "For VCAM-1, 100 μM of G721–0282 inhibited mRNA expression in glioblastoma cells, while the lowest VCAM-1 mRNA was observed in spheroids in the range of 100–25 μM as a trend, without statistical significance." (PMID 39399677, 2024). "Confocal microscopy evidenced a high and specific interaction between fluorescent biotinylated liposomes and glioblastoma cells, overexpressing VCAM-1 after receiving the complete three-step pretargeting treatment." (PMID 38399288, 2024). "Together, these data suggest that CD11a-ICAM-1, CD49a and CD49d-VCAM-1 contribute to the infiltration of subsets of T cells into glioblastoma." (PMID 35464424, 2022). "Human biopsy samples of the brain metastasis and glioblastoma margins were examined for endothelial VCAM-1 expression." (PMID 35312755, 2022). "Our study shows the cells grown in 3D-GMH with serum overexpress and secrete CXCL1, CXCL5, IGFBP2, PTX3, THBS1, VEGFA, and VCAM1—all genes expressed in perivascular or perinecrotic zone of glioblastoma tissues that are hotspots for immune cells." (PMID 34489494, 2021). "Combined ICAM-1/VCAM-1 blockade showed the strongest impairment of T cell infiltration in glioblastoma." (PMID 33262763, 2020). "Additional reports demonstrated that cell adhesion molecule VCAM-1-positive glioblastoma tumor stem cells (GTSC) possess a high rate of proliferation as measured by PCNA expression." (PMID 29089868, 2017). "Recently, a study reported about an EGF-enhanced VCAM-1 expression promoting macrophage and glioblastoma cell interaction and tumor cell invasion." (PMID 25030093, 2014). "In the course of these experiments, we unexpectedly found that the commercially available putative IL13Rα2-specific monoclonal antibody B-D13 recognizes cytokine-induced VCAM-1 on glioblastoma." (PMID 24787244, 2014). "Our research has shown decreasing in VCAM-1 expression in GBM spheroids and also in U-87 MG glioblastoma cells to G721-0282 treatment, mainly at concentrations of 100 − 25 μM, which could be explained by VCAM-1/IL-1β dependence." (PMID 39607670, 2025). "Finally, we show that VCAM-1 is upregulated at the invasive margins of human brain metastasis and glioblastoma samples and extends beyond the tumor margin defined by conventional radiological methods, supporting the potential clinical utility of this approach." (PMID 35312755, 2022). "Our initial aim, therefore, was to determine whether the tumor-brain interface in rat models of brain metastasis and glioblastoma show upregulation of VCAM-1." (PMID 35312755, 2022). "In the glioblastoma samples, the number of VCAM-1–positive vessels significantly increased with closer proximity to the tumor border; although the area of adjacent “uninvolved” brain parenchyma was more limited in the samples, in comparison with the brain metastasis samples." (PMID 35312755, 2022).
glioblastoma (continued). "Finally, we aimed to evaluate the relationship between VCAM-1 upregulation, the tumor margin, and conventional MRI indices in human brain metastasis and glioblastoma samples." (PMID 35312755, 2022). "In glioblastoma, VCAM‐1 expression correlated with the clinicopathological grade of cancer." (PMID 34427969, 2021). "In human glioblastomas, PAK4 reduces the expression of intercellular adhesion molecule 1 (ICAM-1) and vascular cell adhesion molecule 1 (VCAM-1) via SLUG, thereby diminishing T cell adhesion to tumor endothelial cells." (PMID 40332759, 2025). "Our research has observed changes in VCAM-1 expression in response to GBM spheroids and U-87 MG glioblastoma cells to G721–0282 treatment, mainly at concentrations of 100–25 μM, which could be explained by VCAM-1/IL-1β dependence." (PMID 39399677, 2024). "A preliminary confocal microscopy test was performed on glioblastoma cells, naturally overexpressing the adhesion protein VCAM-1, after verifying the VCAM-1 expression levels by using a phycoerythrin-labeled anti-VCAM-1 antibody." (PMID 38399288, 2024). "CD11a and CD49d have been implicated in T-cell glioblastoma-infiltration in a previous study in vitro, where transmigration of T-cells across glioblastoma-isolated ECs occurred in a ICAM-1 and VCAM-1-dependent manner." (PMID 35464424, 2022). "NFκB induces expression of adhesion molecules, including ICAM-1, VCAM-1, and selectins, and NFκB-dependent induction of VCAM-1 was recently reported to promote glioblastoma cell adhesion and invasion." (PMID 24466111, 2014). "This article analyzes for the first time the effects of G721–0282, a CHI3L1 inhibitor, on the expression of proteins involved in intercellular junctions, such as E-cadherin, N-cadherin and VCAM-1, in GBM spheroids composed of glioblastoma U-87 MG cells, macrophages and HMEC-1 endothelial cells." (PMID 39399677, 2024). "In addition, in glioblastoma increased infiltration of CD8+ T cells also correlated with the expression of ICAM-1 and VCAM-1 on the vessel surface Either, ICAM-1 and VCAM-1 blocking antibodies reduced T cell infiltration." (PMID 33262763, 2020).
diabetic retinopathy (17 papers, 2007 to 2025). "For diabetic retinopathy, VCAM-1 and L-selectin were found to be significantly associated with the microvascular complications (OR=0.999, 95%CI=0.997-1.0, p=0.007 and OR=1.0, 95%CI=1.0-1.002, p=0.005, respectively)." (PMID 36843591, 2023). "However, recent studies have implicated VCAM-1 as a major driver of neovascularization in diabetic retinopathy." (PMID 38317227, 2024). "Elevated levels of adhesion molecules such as intracellular adhesion molecule-1 (ICAM-1) and vascular cell adhesion molecule-1 (VCAM-1) are also observed in diabetic retinopathy patients." (PMID 36672234, 2023). "In diabetic retinopathy, the ADAM17-mediated cleavage of CX3CL1 and VCAM-1 in retinal endothelial cells has been associated with vascular leakage and retinal neovascularization." (PMID 37762417, 2023). "In a study by Agardh and Gomez based on animal model of diabetic retinopathy, upregulated VCAM-1 expression in blood vessels was observed in the retina under hyperglycemic conditions." (PMID 37759966, 2023). "ICAM-1 and VCAM-1 mediate leukocyte adhesion to the retinal vasculature, that induces capillary occlusion which has a critical role in the development of diabetic retinopathy (DR)." (PMID 25287126, 2014). "ICAM-1 has been widely used as a marker of endothelial activation in experimental studies of diabetic retinopathy, but much less is known about VCAM-1 in this context." (PMID 20856927, 2010). "The levels of VCAM-1 in the aqueous humor increased with the severity of diabetic retinopathy, which suggests that VCAM-1 may play a role in the progression of diabetic retinopathy." (PMID 34211611, 2021). "Furthermore, CTRP3 inhibits vascular cell adhesion molecule-1 (VCAM-1) expression and could be a potential biomarker for diabetic retinopathy." (PMID 31009504, 2019).
hepatocellular carcinoma (17 papers, 2007 to 2025). A malignant tumor that arises from hepatocytes. "Specific signaling axes such as PI3K-AKT-SELE/VCAM1 and CCL16-CCR1 have been implicated in TAM recruitment in pancreatic ductal adenocarcinoma and hepatocellular carcinoma (HCC),respectively." (PMID 41417432, 2025). "In the liver, CD151 is predominantly expressed in endothelial cells and supports lymphocyte adhesion mediated by the vascular cell adhesion protein 1 (VCAM-1 or CD106) in inflammation and hepatocellular carcinoma." (PMID 36012131, 2022). "For instance, tetraspanin CD151 is upregulated on LSEC by hepatoma-derived factors and collaborates with VCAM-1 to facilitate recruitment." (PMID 32982772, 2020). "Recent studies demonstrated that ANGPTL4 expression in hepatocellular carcinoma can promote transendothelial migration via the upregulation of vascular cell adhesion molecules-1 (VCAM-1)/integrins β1 signaling." (PMID 22481923, 2012). "We propose that CD151 regulates the activity of VCAM-1 during lymphocyte recruitment to the human liver and could be a novel anti-inflammatory target in chronic liver disease and hepatocellular cancer prevention." (PMID 28473332, 2017). "Moreover, our previous study showed that ICAM-1 and VCAM-1 were also expressed in hepatocellular carcinoma (HCC) and promoted HCC cell adhesion to the endothelium." (PMID 26690142, 2015). "Our results revealed that insufficient RFA up-regulated the expression of E-selectin, ICAM-1 and VCAM-1 in TAECs, which suggests that up-regulated adhesion molecules may be the mechanism responsible for the enhanced adhesion of TAECs to hepatoma cells." (PMID 23171368, 2012). "Using a mouse liver carcinoma model, it has been demonstrated, that senescent tumor cells induced innate immune response due to their inflammatory cytokine secretion, accompanied by increase of leukocyte attracting molecules like ICAM1 or VCAM1." (PMID 27448982, 2016). "Recent reports also unveil the role of PI3K-AKT-SELE/VCAM1 axis and CCL16-CCR1 axis in TAM recruitment in pancreatic ductal adenocarcinoma (PDAC) and hepatocellular carcinoma (HCC) respectively." (PMID 40380196, 2025).